SFPQ (splicing factor proline and glutamine rich)
Diseases named in the same sentence as SFPQ in open-access papers (continued):
Sharing a sentence is not in itself a finding about the gene and the disease.
infection (4 papers, 2015 to 2025). The state of being infected such as from the introduction of a foreign agent such as serum, vaccine, antigenic substance or organism. "This association confirms that ZIKV recruits the proviral host factor SFPQ to the perinuclear region, where it colocalizes with the vgRNA during infection." (PMID 40671792, 2025). "This suggested that factors associated with SFPQ in uninfected cells preclude HRV16 RNA interaction and/or a viral factor promotes the association of cleaved SFPQ and HRV16 RNA during infection." (PMID 30142213, 2018). "Aside from the strong evidence for SFPQ redistribution during HRV16 infection, SFPQ is also a compelling candidate for involvement in HRV16 replication due to its association with PTBP1 in uninfected cells." (PMID 30142213, 2018). "As a first step toward describing the role of SFPQ during HRV16 infection, we demonstrated that a C-terminal cleavage product of this protein produced during infection associated specifically with in vitro transcribed, biotinylated HRV16 RNA." (PMID 30142213, 2018). "We found that SFPQ is targeted for proteolysis within the nucleus by viral proteinase 3CD/3C, and a fragment of SFPQ was shown to migrate to the cytoplasm at mid-to-late times of infection." (PMID 30142213, 2018). "One such protein was splicing factor proline and glutamine rich (SFPQ), a C-terminal cleavage fragment of which appeared in the nucleus at mid-times during infection then subsequently relocalized to the cytoplasm." (PMID 30142213, 2018). "In agreement with this, the distribution of SFPQ within the nucleus 4 hours post-HRV16 infection was observed to condense into distinct puncta, suggesting that SFPQ is relocalized within the nucleus, possibly as part of an innate immune response, before it is targeted by 3DC/3C." (PMID 30142213, 2018). "To explore whether SFPQ is a target of 3CD proteinase among the enteroviruses more generally, we tested whether infection with poliovirus resulted in a similar SFPQ cleavage pattern." (PMID 30142213, 2018). "Interestingly, a Mycobacterium tuberculosis protein has been shown to cleave SFPQ following infection, suggesting convergent evolution in either exploiting its extensive functional capabilities or altering host-cell homeostasis to favor pathogen replication." (PMID 30142213, 2018). "Immunofluorescence microscopy confirmed the strong nuclear localization of SFPQ in uninfected HeLa cells and its partial redistribution 8 hours post-infection with HRV16, with SFPQ distributed throughout the cell cytoplasm and nucleus at this time." (PMID 30142213, 2018). "Together, these data suggest SFPQ and histone H1 are not required for initial EBV infection or for the first steps of latency establishment, but that SFPQ and H1 may nonetheless impact the pattern of EBV gene expression at very early stages of infection." (PMID 38755141, 2024). "Mechanistically, SFPQ appears to exert its pro-viral function subsequent to viral translation, as it does not relocate from the nucleus until around the time PTBP1 is cleaved and viral RNA synthesis has commenced, about 6–8 hours post-infection." (PMID 30142213, 2018). "We show here that the redistribution of SFPQ as a result of HRV16 infection does not occur until after peak times of viral protein production during the infectious cycle." (PMID 30142213, 2018). "Several infection-induced SUMO targets also are involved in mRNA maturation events, such as 3′ end pre-mRNA processing (CPSF1, CPSF2, FIP1L1, RBBP6, and WDR33), splicing (CLASRP, SFPQ, and ZRANB2), and nuclear RNA quality control (ZC3H18, ZCCHC7, and PAPD5)." (PMID 26549460, 2015). "However, SFPQ has also been shown to concentrate in nuclear foci upon treatment with actinomycin D, suggesting that the HRV16-induced transcriptional repression could also account for the nuclear puncta observed 4 hours post infection." (PMID 30142213, 2018).
neurological disorders (3 papers, 2017 to 2025). "SFPQ is expressed in both the cytoplasm and nucleus, and aberrant SFPQ expression is potentially associated with many diseases, such as neurological disorders and malignancies." (PMID 39856764, 2025). "Furthermore, SFPQ has been associated to diverse neurological diseases, such as ALS and FTLD, and may prove to be a critical for maintaining the circRNAome in these and other neurodegenerative pathologies." (PMID 33476259, 2021). "Neuronal homeostasis may be dependent upon a complex balance between nuclear and extra-nuclear RNA processing events controlled by proteins such as SFPQ, HNRNPA2, U1 snRNP70, and FUS, a balance that, when disturbed, may contribute mechanistically to a wide range of neurological disorders." (PMID 28392072, 2017).
neurodevelopmental disorder (2 papers, 2017 to 2023). A behavioral and cognitive disorder with onset during the developmental period that involves impaired or aberrant development of intellectual, motor, or social functions. "We also discerned further correlates between circRNAs and neurodevelopmental disorders and identified the splicing factor SFPQ as an important player in neuronal maturation, as both a regulator of circRNA levels and possibly a target of circRNA regulation itself." (PMID 37237280, 2023).
cardiovascular diseases (1 paper, 2021). "At least 6 critical genes, namely CTNNB1, HNRNPA1, SRSF4, TRA2A, SFPQ, and RBM5, and two large clusters of biological terms which are associated with the cardiovascular diseases are deregulated in the presence of omeprazole." (PMID 34659661, 2021).
SFPQ also shares sentences with these, for which no sentence is quoted: Pick disease (3 papers); autism spectrum disorder (2); glioblastoma (2); intellectual disabilities (2); Parkinson's (2); adenocarcinoma (1); bipolar disorder (1); breast carcinoma (1); Burkitt lymphoma (1); Cerebral ischemia (1); cystic fibrosis (1); cytomegalovirus infection (1); Down syndrome (1); esophageal cancer (1); gastric adenocarcinoma (1); hantavirus infection (1); HIV-1 infection (1); Huntington disease (1); idiopathic pulmonary fibrosis (1); lymphoma (1); metastatic disease (1); metastatic melanoma (1); myocardial infarction (1); non-Hodgkin lymphoma (1); papillary 1 renal cell carcinoma (1); papillary renal cell carcinoma (1); progressive supranuclear palsy (1); steatosis (1).